NUP62 (nucleoporin 62)
Diseases named in the same sentence as NUP62 in open-access papers (continued):
Sharing a sentence is not in itself a finding about the gene and the disease.
tumor (7 papers, 2020 to 2026). "Further stratification according to patients’ clinical characteristics revealed that NUP62 is associated with the stages of multiple cancers, suggesting its role in tumor progression, invasion, and metastasis." (PMID 40098960, 2025). "In summary, this study revealed the expression characteristics of NUP62 in multiple malignancies and its associations with tumor-related pathways, clinical features, prognosis, and tumor immunity." (PMID 40098960, 2025). "Subsequently, we detailed the specific effects of various compounds on NUP62 in different tumor types and highlighted the significant diagnostic and prognostic predictive value of NUP62 in these tumor types." (PMID 40098960, 2025). "Specifically, it reversed enhancement in tumor growth, mass, and expression of downstream genes (NUP62, NUP93, and NUP98), accompanied by modulation of NPC numbers and Ki-67 or CD31 labeling index." (PMID 41510169, 2026). "Tools such as SangerBox, TIMER 2.0, and GSEA were employed to evaluate the relationship between NUP62 and the tumour immune microenvironment, as well as its involvement in signalling pathways." (PMID 40098960, 2025). "We found that arachidonyltrifluoromethane significantly impacts NUP62 expression across multiple tumor types." (PMID 40098960, 2025). "In the future, further in-depth studies can be conducted to investigate how NUP62 interacts with immune-related genes and how these interactions affect the tumor immune microenvironment and immunotherapeutic effects." (PMID 40098960, 2025). "The results indicated that compared to normal tissues, the expression level of NUP62 in tumor tissues exhibited a significant upward trend." (PMID 40098960, 2025). "In KIPAN and LIHC, differences in NUP62 expression are observed among tumor patients with different T stages." (PMID 40098960, 2025). "The discovery of compounds that can significantly modulate NUP62 activity holds important potential value for developing novel and effective tumor treatment regimens." (PMID 40098960, 2025). "Functional analyses showed that NUP62 is involved in cell cycle regulation, DNA damage repair, and tumour immunity." (PMID 40098960, 2025). "Simultaneously, our research also revealed that the expression of NUP62 is significantly correlated with the infiltration levels of various immune cells, indicating that NUP62 can regulate the tumor immune microenvironment by influencing immune cells." (PMID 40098960, 2025). "In vivo, eribulin or NUP62 silencing significantly suppressed tumor growth in xenograft models." (PMID 42016308, 2026). "By regulating the expression or function of NUP62, it may be able to influence the activity of immune cells and the immune status in the tumor microenvironment, thus providing new strategies for immunotherapy." (PMID 40098960, 2025). "The analysis results indicated that NUP62 may be involved in various tumor-related pathways and metabolic regulatory processes, such as the G2/M checkpoint, E2F transcription factor target genes, allograft rejection, and mitotic spindle formation." (PMID 40098960, 2025). "The mechanistic basis involves ARMC12, which functions within liquid-liquid phase-separated condensates to co-activate MYC, driving the subsequent up-regulation of NUP62, NUP93, and NUP98, elevation of NPC number, and tumor progression." (PMID 41510169, 2026). "The O-HDPSCs overexpressing NUP62 did not increase in tumor volume compared to those transfected with empty vector." (PMID 40246825, 2025).
neurodegenerative disease (5 papers, 2021 to 2025). A disorder of the central nervous system characterized by gradual and progressive loss of neural tissue and neurologic function. "TDP-43 inclusions are a neuropathological feature of several neurodegenerative diseases; thus NUP62’s role in promoting TDP-43 insolubility may be broadly relevant to a variety of neurodegenerative disorders." (PMID 35697676, 2022). "We examined postmortem brain tissue from patients with mild (nine cases) and severe CTE (nine cases) and aged-matched controls (eight control cases) without neurodegenerative disease for NUP62 pathology in the frontal cortex." (PMID 34060470, 2021). "(A) NUP62 immunohistochemical staining in human frontal cortex tissue from a control individual without neurodegenerative disease, showing faint perinuclear staining for NUP62 (arrow)." (PMID 34060470, 2021).
nervous system disorder (3 papers, 2023 to 2025). A non-neoplastic or neoplastic disorder that affects the brain, spinal cord, or peripheral nerves. "First, we examined markers for different compartments of the NPC which have been shown to been altered in neurologic diseases, including Nup62 and Nup98 in the central channel, POM121 to demarcate the transmembrane ring, and RanBP2 within the cytoplasmic ring and filaments." (PMID 39452051, 2024). "In conclusion, Nup62 pathology may be a common event in various nervous system disorders." (PMID 36908815, 2023).
NUP62 also shares sentences with these, for which no sentence is quoted: squamous cell carcinoma (3 papers); primary biliary cirrhosis (2); adrenocortical carcinoma (1); autoimmune hepatitis (1); bladder cancer (1); Bladder Urothelial Carcinoma (1); clear cell renal carcinoma (1); Esophageal Carcinoma (1); frontotemporal lobar degeneration (1); liver cancer (1); lung adenocarcinoma (1); melanoma (1); myositis (1); osteoarthritis (1); preeclampsia (1); prostate carcinoma (1); rheumatic diseases (1); skin cutaneous melanoma (1); steroid-resistant nephrotic syndrome (1); vasculitis (1).